TERT (telomerase reverse transcriptase)
Diseases named in the same sentence as TERT in open-access papers (continued):
Sharing a sentence is not in itself a finding about the gene and the disease.
cancer (continued). "The increased expression of the TERT gene, which significantly improves cancer cell survival, is associated with an altered regulation of a number of apoptotic signaling proteins." (PMID 37189709, 2023). "Overexpression of TERT causes cancer progression via facilitating cellular proliferation, bypassing cellular senescence, and lengthening of telomeres." (PMID 38163482, 2023). "The presence of TERT mutations has been shown to be associated with poor prognosis in patients with different types of cancer." (PMID 37298294, 2023). "The telomerase reverse transcriptase (TERT) gene is one of the essential polymorphic loci linked to various human cancers." (PMID 38084250, 2023). "TERT-promoter mutation leads to the upregulation of TERT transcription, which enables cancer cells to avoid cell senescence and increase their replication potential." (PMID 36937322, 2023). "Therapeutic strategies specifically directed to TERT promoter mutations will likely have an important clinical impact in many types of human cancers characterized by such mutations." (PMID 38033865, 2023). "TERT promoter mutations (TPMs) are cancer type-specific and among the first few mutations reported in melanomas, glioblastomas and hepatocellular carcinomas." (PMID 36899924, 2023). "While the VNTR polymorphism of TERT has been investigated in relation to cancer susceptibility, the VNTR polymorphism of CLPTM1L remains unexplored." (PMID 38254939, 2023). "Point mutations at the promoter region of the telomerase reverse transcriptase (TERT) gene is one of the most frequent non-coding mutations in cancer." (PMID 36899924, 2023). "The aggressive morphology of the carcinoma component on the one hand and the presence of the TERT mutation on the other hand indicate a rather unfavorable prognosis of the patient." (PMID 37249797, 2023). "In recent years, many studies have confirmed the relationship between TERT promoter mutations and maintenance of telomerase activity, as well as the occurrence, progression, and prognosis of cancer." (PMID 35903534, 2022). "In 2013, two seminal studies unravelled the hotspot TERT promoter mutation as a novel mechanism for TERT expression and telomerase activation in human cancer." (PMID 36713366, 2022). "The role of ETS in TERT gene expression has been confirmed independently in cancer patients with C→T nucleotide mutations creating additional ETS binding sites and mechanistically." (PMID 35269498, 2022). "Despite the major challenges, TERT promoter mutations and telomerase remain attractive targets for cancer treatment." (PMID 35903534, 2022). "In contrast, in human cancer cell lines, knockdown of TERT causes a rapid decline in cell proliferation and growth." (PMID 35903534, 2022). "These can modulate the activity of clinically important genes, as recently shown for the telomerase gene (TERT), where promoter mutations have been associated with a variety of cancers." (PMID 35573091, 2022). "Mutations in the telomerase reverse transcriptase (TERT) promoter region are frequently observed in specific types of human cancers, leading to enhanced expression of telomerase." (PMID 35135543, 2022). "The enzyme responsible for expanding telomere repeats, telomerase (TERT), is commonly subjected to mutation or dysregulation in cancer." (PMID 36230545, 2022). "To date, the C228T and C250T hotspot mutations have been identified in over 50 distinct types of cancer, and they are responsible for the activation of the TERT promoter region and TERT gene transcription." (PMID 35135543, 2022). "TERT rs2736100 genetic polymorphism is commonly found in human malignancies, indicating its key role in cancer cell transformation." (PMID 36704521, 2022). "Whole-genome association studies have identified the TERT gene rs401681 as one of the most significant cancer-associated SNPs." (PMID 35892421, 2022).
cancer (continued). "CTC number 12 months after RC and VAF of the TERT c.-124C > T mutation were significant predictors of cancer specific survival (CSS)." (PMID 35713686, 2022). "Several cancer-related genes are located within genomic regions of increased susceptibility, including telomerase reverse transcriptase, TERT, thereby accelerating mutagenic potential in cancers with RB1 pathway alterations." (PMID 34983823, 2022). "Cancer cell lines with the wild-type TERT express either one or both alleles, on a case-by-case basis." (PMID 36011010, 2022). "Considering the decisive role of these mutations, TERT has been considered a promising target for drug development; therefore, studying TERT mutations is important for cancer prevention, screening, early diagnosis, and targeted gene therapy." (PMID 35053139, 2022). "Hypermethylation of specific regions has been confirmed as associated with TERT mRNA expression in breast, colorectal, and other cancers." (PMID 35158835, 2022). "Later, this domain was referred to as THOR (TERT hypermethylated oncological region), involved in the cancer-associated transcription of TERT." (PMID 35327497, 2022). "Because TERT promoter mutations are so common in cancer cells, it is crucial to understand their significance for cell growth and tumorigenicity." (PMID 35328421, 2022). "Mutations in the TERT gene can alter telomerase activity and telomere length, inducing bone marrow failure syndromes and significantly increasing cancer frequency." (PMID 35328597, 2022). "Much of the previous interest in TERT allele-specific expression and promoter methylation in cancer has focused more on TERT mutant samples." (PMID 36011010, 2022). "As in cancer, these mutations at the TERT promoter increase TERT transcription only marginally (by twofold or less), but nonetheless this increase is still sufficient to delay replicative senescence in human fibroblasts." (PMID 35920280, 2022). "The most common genetic signature of HCC is mutation of the Telomerase (TERT) gene which is present in around 60% of cancers and is the earliest detectable of all the known mutations." (PMID 35739588, 2022). "Various mechanisms, including genetic mutations and epigenetic changes, have been proposed to explain the pleiotropic association of the 5p15.33 region in which the TERT gene resides with telomerase activity and cancer predisposition." (PMID 35563554, 2022). "The most common noncoding alterations in cancer are somatic mutations in the telomerase reverse transcriptase (TERT) promoter region." (PMID 35326649, 2022). "In vitro and in patient database analyses, we demonstrate that low Msi-1 is linked to a decrease in Notch-1, DNA-PKcs and TERT, all related to cancer stem cells and therapy resistance, and an increase in p21, an anti-proliferative marker." (PMID 35619161, 2022). "The hypermethylation of a specific region within the hTERT promoter, termed TERT hypermethylated oncological region (THOR) has been associated with increased hTERT expression in cancer." (PMID 36529814, 2022). "It is interesting to note that the core promoter-mutated TERT causes its increased expression in multiple types of cancer, including in our expression analysis." (PMID 35033028, 2022). "It is recognized that TERT can become prone to reactivation with aging and progressive telomere shortening, increasing the risk of cancer." (PMID 35953846, 2022). "Reactivation of TERT expression is a hallmark of cancer development and is observed in more than 80–90% of tumors." (PMID 35892421, 2022). "TERT promoter mutations have been reported to be associated with aggressive behavior and poor outcome in various types of cancers." (PMID 34558656, 2022). "Although unique fragment coverage for TERT promoter centered around cancer-associated TERT promoter mutations, the nature of anchored multiplex PCR did result in coverage beyond the target region albeit with lower read depth." (PMID 35494035, 2022).
cancer (continued). "Literature reports positive associations between both cancerous and non-cancerous diseases concerning telomeres and the TERT gene due to either dysfunction or abnormal reactivations of telomerase activity." (PMID 36415512, 2022). "TERT promoter mutations control the apoptosis of BRAF mutant cancer cells, thereby controlling the therapeutic response to BRAF/MEK inhibitors." (PMID 35903534, 2022). "We showed that TERT allele-specific expression is amenable to in vitro epigenetic manipulation in wild-type cancers." (PMID 36011010, 2022). "In many common types of cancer, telomerase is reactivated through a mutation in the promoter of telomerase reverse transcriptase (TERT)." (PMID 36130485, 2022). "Transcriptional activation of TERT via mutation in the promoter region or other mechanisms limits the production of active telomerase in many human cancers." (PMID 35135543, 2022). "Accordingly, most cancer genes show less mutations and copy number changes in AYAs, including the noncoding TERT promoter mutations." (PMID 36433963, 2022). "Surprisingly, we found that both alleles in wild-type cancer cell lines (including the bi-allelically expressed Ku1919 cell line) had symmetrically high methylation levels at the TERT distal promoter." (PMID 36011010, 2022). "TERT promoter mutations are the most common noncoding alterations in cancers, although some remain to be characterised." (PMID 36114166, 2022). "The most characterized somatic non-coding mutation in human cancer is the TERT (telomerase reverse transcriptase) promoter, which is recurrently mutated in more than 50 individual cancer types." (PMID 36171609, 2022). "While various concerns have been voiced regarding TERT therapy, one issue that has been repeatedly raised is that of the possible risk of cancer induction." (PMID 36552277, 2022). "First identified pathogenic alterations associated with TERT re‐expression in cancer were the c.‐124C>T (C228T) and c.‐146C>T (C250T) TERT promoter mutations." (PMID 35979662, 2022). "It has recently been identified that cancer cells display an allele-specific activation of the TERT transcription, leading to biallelic or monoallelic expression (BAE or MAE) of TERT." (PMID 36713366, 2022). "In sharp contrast, switching C228T to a WT sequence in cancer cells resulted in downregulation of TERT expression and loss of tumorigenesis." (PMID 36713366, 2022). "It is well known that abnormal telomerase activity plays a crucial role in the development of several cancers, and the TERT gene encodes a reverse transcriptase of the telomerase complex." (PMID 35328597, 2022). "The TERT gene is thought to be involved in an apoptotic response, and its level of expression affects the susceptibility of cancer cell lines to anticancer drugs." (PMID 35892421, 2022). "Activation of TERT expression in cancer can be induced through non-coding point mutations in the promoter sequence, leading to telomere lengthening." (PMID 36230545, 2022). "Regardless of the importance of core promoter in controlling gene expression, however, TERT remains as the only gene with established relationship between core promoter mutation and cancer." (PMID 35033028, 2022). "Mutations in the proximal promoter of TERT (telomerase reverse transcriptase) are the first genomic lesions in a gene regulatory region and display a high prevalence across multiple cancer types." (PMID 35053525, 2022). "We first sought to determine if TERT promoter genetic alterations (i.e., promoter mutations or structural rearrangements) and the cancer-associated (distal) promoter methylation are mutually exclusive in clinical cancer specimens." (PMID 36011010, 2022). "In a previous study, reverting TERT promoter mutation has been reported to inhibit telomerase activity and growth of cancer cells." (PMID 35053139, 2022).
cancer (continued). "Several studies are attempting to specifically target cancer cells harbouring TERT promoter mutations, for example, by suppressing GABPβ1L-driven transcription at these de novo ETS binding sites." (PMID 36741696, 2022). "The catalytic subunit of telomerase TERT is overexpressed by cancer cells and has been considered as a potential cancer associated antigen." (PMID 35409143, 2022). "TERT genetic alterations include heterozygous cis-activating TERT promoter point mutations—the most frequent non-coding mutation in cancer— and TERT structural variations (i.e., rearrangements, amplifications)." (PMID 36011010, 2022). "We compared the core promoter-mutated genes with altered gene expression to the cancer driver gene list and observed that the somatic-mutated TERT and PRRX1, and germline-mutated GAB2 were on the list." (PMID 35033028, 2022). "One means by which this loss can be overcome in stem cells and cancer cells is via re‐addition of G‐rich telomeric repeats by the telomerase reverse transcriptase (TERT)." (PMID 35920280, 2022). "In many eukaryotic cells, including stem cells and cancer cells, this loss is often counteracted by the expression of the telomerase reverse transcriptase (TERT) and its integral RNA template component hTR (encoded by TERC)." (PMID 35920280, 2022). "TERT promoter mutations occur in various types of cancer and create de novo ETS binding motifs recognized by the GABPA-containing complex." (PMID 35549739, 2022). "Careful isolation of the cells with different shapes and subculture identified the same TERT promoter mutation in both cells, implying they were both cancer cells descended from a common ancestor." (PMID 35278143, 2022). "TERT codes a telomerase subunit and affects the regulation of telomerase activity, causing the oncogenic progression of various cancers." (PMID 35954337, 2022). "Given the requirement of GABPA and GABPB1 to activate the mutated TERT promoter, they have been suggested as targets for telomerase-based cancer therapy." (PMID 36713366, 2022). "While clinical trials will determine the actual risk of TERT gene therapy, it appears to be misrepresented for cancer-free recipients." (PMID 36552277, 2022). "Great efforts have thus been made to elucidate regulatory mechanisms underlying TERT transcription and its role in cancer development and/or progression." (PMID 36713366, 2022). "In this review, we recapitulate on recent findings on virus–telomerase/telomeres interplay and the importance of TERT-related oncogenic pathways activated by cancer-causing viruses." (PMID 36358677, 2022). "As a proof of concept, a “universal” cancer DNA vaccine was produced comprising an amplicon expression vector encoding an optimized version of telomerase reverse transcriptase (TERT)." (PMID 35668533, 2022). "The prevalence of abnormal type 53BP1 expression and NRAS and TERT-p mutations in PDc was comparable to that of carcinomas." (PMID 35892838, 2022). "A pan-cancer study reported that TERT alterations including promoter mutations, amplifications and structural variants were seen in ~30% of all cancers." (PMID 34824250, 2021). "The maintenance of telomeres constitutes one of the hallmarks of cancer, and the presence of TERT mutation is generally associated with disseminated disease." (PMID 34108637, 2021). "Recent studies have investigated the role of TERT promoter mutations in cancer diagnosis, prognosis, and predictor of radiotherapy resistance." (PMID 33776938, 2021). "In contrast to other cancers, mutations in the TERT promoter region are rare in NB primary tumors and cell lines." (PMID 34439779, 2021). "56.0% of cancer patients and 6.1% of non-cancer patients had TERT promoter hot spot mutations (C228T and C250T), the difference was statistically significant (P<0.05)." (PMID 33854611, 2021). "The mechanisms of TERT induction in cancer cells are numerous and diverse, including promoter mutation and epigenetic regulation." (PMID 35223454, 2021).
cancer (continued). "Rearrangements in TERT upstream and downstream regions would cause TERT overexpression by genomic repositioning, acting as potent cancer driver mutations." (PMID 34884690, 2021). "Somatic mutations in noncoding sequences are poorly explored in cancer, a rare exception being the recent identification of TERT promoter mutations." (PMID 33851100, 2021). "Recently, TERT promoter mutations have been frequently found in multiple cancer types and predict poor patient prognosis." (PMID 33483600, 2021). "Somatic mutations (TERT promoter mutations) are often detected at the proximal promoter site of TERT in cancer cells." (PMID 34477310, 2021). "Consistently, hypermethylation of the TERT promoter alleles signals transcriptional repression of those alleles, leading to attenuation of TERT activation in cancer cells." (PMID 33413203, 2021). "Genome-wide association studies have identified multiple variants at the TERT locus that are associated with telomere length and risk of several cancers." (PMID 34067464, 2021). "Beyond raw gene and transcript expression levels, we next examined the underlying mechanisms for reactivating TERT in cancer using the comprehensive cell line data." (PMID 34486523, 2021). "Genetic mechanisms contribute to the regulation of TERT in cancer through promoter mutations, gene copy number variations, and genomic rearrangements." (PMID 33802026, 2021). "Human telomerase reverse transcriptase (TERT) gene promoter mutations have been observed in multiple types of malignant tumors." (PMID 34108637, 2021). "In contrast TERT deficiency in fibroblasts reduced fibroproliferation and tissue remodeling of potential import in cancer." (PMID 34253690, 2021). "In a preclinical study, application of an ABE corrected a point mutation in the TERT (telomerase reverse transcriptase) promoter that is found in many types of cancer." (PMID 34199901, 2021). "These PCR products underwent Sanger sequencing to identify any known cancer-associated mutations in the TERT promoter." (PMID 33707600, 2021). "Through our analysis, we show relevant markers of telomere-associated protein function, patterns of TERT reactivation across cancers, and epigenetic determinants of TERT promoter status." (PMID 34486523, 2021). "Several nucleotide mutations are frequently introduced in the TERT promoter region and implicated in telomerase reactivation in cancer cells by the de novo binding sites for ETS family transcription factors such as GABP8–10." (PMID 34489496, 2021). "The key rate-limiting element for telomerase activity was found to be TERT, encoding an essential catalytic subunit of telomerase that is aberrantly expressed in many types of cancer." (PMID 34858826, 2021). "Increased telomerase activity is known to be one of the primary characteristics of human cancers, and the transcriptional mediation of the TERT gene is the main cause for its cancer-specific activation." (PMID 34368047, 2021). "While individual TERT SNPs have been associated with different types of cancer and telomere length and a common haplotype with decreased cancer risk substantially reducing TERT promoter activity." (PMID 34059744, 2021). "Many studies have confirmed that somatic mutations and functional SNPs of TERT genes are associated with multiple cancer risks." (PMID 34858826, 2021). "It has been reported that the rs2242652 allele of TERT influences telomere length, which has in turn been linked to a number of diseases including cancers." (PMID 34048184, 2021). "Given that p-Sp1 and GABPA can be recruited to mutant TERT promoter with high cooperativity, thus we suppose that Sp1 and GABPA synergistically activate mutant TERT promoter in cancer cells carrying both BRAFV600E and TERT promoter mutations." (PMID 33483600, 2021). "TERT promoter mutations and TERT reactivation are generally monoallelic, suggesting that TERT reactivation on one allele is sufficient to counteract telomere attrition in cancer cells." (PMID 34944589, 2021).